PCNA (proliferating cell nuclear antigen)
Diseases named in the same sentence as PCNA in open-access papers (continued):
Sharing a sentence is not in itself a finding about the gene and the disease.
cancer (continued). "Combining PCNA inhibitors with some conventional anti-cancer therapies, such as chemotherapy, radiotherapy, and immunotherapy, shows synergistic effects and promises improved overall therapeutic outcomes." (PMID 41024300, 2025). "Building on this discovery, AOH1160 was developed as a small molecule inhibitor targeting the L126-Y133 region of PCNA, a site altered in cancer cells that forms a unique binding pocket for proteins." (PMID 41170373, 2025). "Here, we demonstrate a novel function of CHAF1A in regulating PCNA K164 monoubiquitination mediated-TLS pathway in cancer cells." (PMID 40025006, 2025). "A previous study demonstrated that PCNA is essential for maintaining cancer stemness through Y211 phosphorylation." (PMID 41024256, 2025). "In conclusion, PCNA emergesas a co-oncogene and an indispensablepan-cancer prognostic biomarker in our investigation." (PMID 40657100, 2025). "Beyond protein expression, genomic profiling reveals that PCNA is subject to diverse alterations across human cancers." (PMID 41170373, 2025). "Modification of cancer biomarkers, such as decreased PCNA and Ki-67, increased Bax/Bcl-2 ratio, increased cleaved caspase-3, decreased VEGF and CD31, and decreased matrix metalloproteinases, especially MMP-2 and MMP-9, were also observed." (PMID 41322296, 2025). "In tumors, PCNA facilitates cell cycle regulation and progression by ensuring efficient DNA replication and repair, which correlates with cancer development and progression." (PMID 41024300, 2025). "Collectively, theseanalyses offer a comprehensive functional landscape of PCNA’sinteraction network, highlighting its involvement in key oncogenicpathways and potential as a therapeutic target in cancer progression." (PMID 40657100, 2025). "Given the limited frequency of PCNA genetic alterations,its overexpression in cancers is likely driven by deregulated signalingpathways rather than direct genomic alterations." (PMID 40657100, 2025). "Although the role of PCNA incontrol of DNA homeostasis has been extensively studied in some cancers,its pan-cancer relevance in tumorigenesis, immune interactions, andtherapeutic resistance remains underexplored." (PMID 40657100, 2025). "Similar to PCNA, PARP1 is another important DNA repair signaling molecule that is overexpressed in many cancers and associated with poor prognosis." (PMID 40313621, 2025). "We reveal that the arginine methylation dynamics of FEN coordinates the sequential binding of the core OFM enzymes to PCNA, which is crucial to minimizing PARP1-LIG3-induced genome-wide duplication and point mutations, which are often observed in cancer cells." (PMID 41280084, 2025). "Evidence suggests that PCNA, when expressed on the surface of cancer cells, can interact with NKp44 to inhibit the antitumor function of NK cells." (PMID 41024300, 2025). "In rapidly dividing or treatment-resistant cancer cells, PCNA expression and activity are often elevated, reflecting high demands for DNA replication and damage repair." (PMID 41190241, 2025). "ATX-101, a novel cell-penetrating peptide containing APIM, is a PCNAi that disrupts PCNA-protein interactions and has shown significant anti-cancer activity as a single agent in multiple cancer cell lines and models." (PMID 41024300, 2025). "Our exhaustive investigation uncovered distinct PCNA expressionpatterns across multiple cancer types, with significant overexpressionobserved in the bladder, colon, esophagus, lung squamous cell, rectum,stomach, and testis." (PMID 40657100, 2025). "PCNA is overexpressed across a wide spectrum of cancers, including breast, lung, liver, and colorectal malignancies, where its levels often correlate with poor prognosis." (PMID 41170373, 2025). "Further investigation with cancer tissues showed that the down regulation of Ki67 as well as PCNA after FOLFOX treatment were significantly reversed in high salt diet groups." (PMID 39972411, 2025).
cancer (continued). "Emerging evidence indicates that PCNA drives the malignant progression of cancer through modulating various pathophysiological processes." (PMID 40313621, 2025). "Among the proliferation‐associated genes analyzed—including MKI67, PCNA, MCM2–7, MAP17 (PDZK1IP1), and PLK1—many demonstrated strong positive correlations with C1GALT1 expression in cancers such as pancreas, bladder, breast, stomach, prostate, and liver." (PMID 40548474, 2025). "The expression levels of PCNA are also often used as an indicator of cell proliferation activity, and plays a significant role in cancer diagnosis and prognosis." (PMID 39895780, 2025). "On the other hand, the enhanced expression of PCNA and Ki67 was observed in cancer tissues compared with normal lungs in Lewis cell-bearing mice." (PMID 38778121, 2024). "Although PCNA is present in all cells, it exists as three main subtypes, with differences in the quantity of expression in cancer cells." (PMID 39205238, 2024). "In fact, Ki-67 and PCNA were widely used in clinical diagnosis and laboratory animal studies of human cancers, especially within the xenograft mice model." (PMID 38499634, 2024). "Activated STAT3 signaling is known to regulate essential cancer cell mechanisms such as proliferation, survival, and metastasis pathways by modulating genes involved in cell proliferation (PCNA), the cell cycle (Cyclin D1), and apoptosis (PARP and Caspase 3)." (PMID 39273033, 2024). "ELISA analysis of PCNA protein levels in MCF-7 and HepG2 cells confirmed immunofluorescence staining and showed that the amount of PCNA protein was meaningfully reduced in cancer cells incubated with 30 μM 7-KSS for 24 h vs. control and DMSO groups." (PMID 39065711, 2024). "Ki67 and PCNA are representative proliferation-related molecular markers, which are widely used to evaluate the proliferative capacity of cancer cells." (PMID 38725628, 2024). "Given its role in DNA repair, the relationship with PCNA and cancer cells is thought to play a key role in both carcinogenesis and subsequent cancer growth and metastases." (PMID 39205238, 2024). "PCNA, a cofactor of DNA polymerase, is necessary for cell proliferation and has a significant role in the increase of numerous cancers, including CRC." (PMID 38958363, 2024). "Kaempferol has been observed to inhibit cell growth by inducing apoptosis in cancer cells, notably through the downregulation of proliferating cell nuclear antigen (PCNA) and activation of cleaved caspase-3 pathways." (PMID 38730663, 2024). "We found that P4HA3 expression was positively correlated with the typical proliferation proteins, including proliferating cell nuclear antigen (PCNA) and Ki-67 in various of cancers, such as BLCA, BRCA, HNSC, KICH by the heat map (P < 0.05)." (PMID 39504328, 2024). "Within cancer cells, PCNA can be found on the cell surface, in the cytoplasm, and the perinuclear area." (PMID 39205238, 2024). "Arbutin prevented cancer also by down-regulating PCNA and up-regulating the expression of the Bax protein." (PMID 38958363, 2024). "We also observed a decrease in the PCNA index in cancer cells and a reduction in α-SMA and sirius red staining." (PMID 38715057, 2024). "Similar to Ki67, a greater expression of PCNA was found in cancers with large tumor size, higher histological grade, skin ulceration, and the presence of metastasis." (PMID 38474142, 2024). "Microcells that have detected PCNA expression and RNA synthesis can tolerate applied therapy with cancer stem cell properties." (PMID 39062149, 2024). "This suggests that although PCNA is present in all cells, PCNA has an important role in oncogenic regulation and development within cancer cells." (PMID 39205238, 2024).
cancer (continued). "PCNA is a protein expressed in a specific phase of the cell cycle and is generally considered to be positively correlated with cancer cell proliferation." (PMID 38510491, 2024). "EGFR-mediated HSP70 nuclear localization and HSP70-assisted assembly of the PCNA-centered replisome are important mechanisms for cancer-initiating cells to reduce replication stress for their proliferation." (PMID 39470734, 2024). "For decades, nuclear antigen Ki-67 and PCNA were recruited as the most popular proliferation markers for numerous human cancer studies worldwide." (PMID 38499634, 2024). "CDK1, CCND1, and PCNA play distinct roles in different phases of cell cycle and have been identified as pivotal genes in the development and progression of different cancer types, including colon, liver, and gynecological tumors." (PMID 38831458, 2024). "Inhibiting DIO3OS expression by blocking the DIO3OS/let-7d/NF-B2 axis, which lowers the expression of ki-67 and PCNA and reduces cancer cell viability." (PMID 37470034, 2023). "Second, the fluorescent images labeled for the detection of PCNA in cancer cells indicated cell proliferation." (PMID 37463912, 2023). "It has been widely reported that CHAF1A and PCNA co-regulate histone assembly to promote cancer progression." (PMID 37189802, 2023). "IMMT levels positively correlated with biomarkers linked to cancer proliferation (KI67, PCNA, and MCM2) and with key regulators of the cell cycle (CDK4, CDK2 and CDK1)." (PMID 36899366, 2023). "The results of immunohistochemistry assays proved that COX-2 overexpression significantly improved PCNA expression, which presents for cancer cells proliferation, and α-SMA and FN1 expression in mesenchyma." (PMID 37723559, 2023). "We’re also checking if blocking PCNA with mAb14 affects the immune cells’ ability to kill these cancer cells." (PMID 37686697, 2023). "The hit list in our screen reassuringly contained many well-known cancer genes such as PCNA, CDK1 and PLK1, further demonstrating the validity of the screen results." (PMID 37161535, 2023). "Prof. Porgardor’s research team previously revealed that the presence of NKp44 on NK cells leads to the recruitment of the fraction of PCNA localized on the plasma membrane of cancer cells into the NK immunological synapse." (PMID 37686697, 2023). "Through expression of proliferating cell nuclear antigen (PCNA) and E-cadherin, Cu-Cy NPs inhibited cancer cell proliferation and migration in a dose-dependent manner, with no obvious toxicities in vivo." (PMID 36903549, 2023). "PCNA, a prognosis marker in diverse cancers, and some studies demonstrated that the elevated expression of PCNA is linked with the malignancy of EOC." (PMID 37818040, 2023). "Since multiple PTMs of PCNA interrupt its chromatin binding ability, developing therapeutics of modified PCNA will be conducive to target cancer cells." (PMID 36776764, 2023). "PCNA is an ubiquitous eukaryotic protein essential for DNA replication and DNA repair, and its inhibition is considered to be a promising anti-cancer strategy." (PMID 37371061, 2023). "PCNA and Ki67 are cell cycle-specific antigens and prognostic proliferation standard markers for several types of cancer." (PMID 37233859, 2023). "The inhibited cell proliferation in the LV-KIAA1456-derived cancers was further corroborated by ki67 and PCNA levels." (PMID 37056382, 2023). "Effective cellular stress responses allow cancer cells to escape anti-cancer therapies; thus, disabling the stress-driven scaffold functions of PCNA is an attractive approach for anti-cancer treatment." (PMID 36564469, 2023). "Knockdown of CHAF1A or PCNA significantly inhibits EC cell proliferation and DNA replication rates, which is consistent with studies in other cancers." (PMID 37189802, 2023). "The volcano plot of DEGs between 11 wart and 7 cancer samples of patients with EV shows differential expression of cancer-associated genes, such as FOS, JUND, PCNA, CHEK1, and CDKN2A." (PMID 36602881, 2023).
cancer (continued). "Given that it is already established as a useful prognostic and diagnostic biomarker or an effective therapeutic target in various cancers, substantial efforts have been made to develop novel approaches targeting PCNA for cancer therapy." (PMID 36430528, 2022). "Post-translational modifications are crucial for the PCNA function, significantly, that PCNA exists in an alternative methylated form in cancers." (PMID 36142875, 2022). "Owing to the large number of proteins that can interact with PCNA, as well as its role in cell proliferation, the role of PCNA in cancer is of great interest." (PMID 36360296, 2022). "The increased expression of PCNA is highly noticed in proliferating cells, including cancer cells, and it serves as a clinical marker for malignancy." (PMID 35563109, 2022). "Our study demonstrates a novel function of PCNA as an essential factor for maintaining cancer stemness through Y211 phosphorylation." (PMID 35628489, 2022). "The proliferation status of cancer cells was further confirmed by the detection of proliferating cell nuclear antigen (PCNA) through immunohistochemical analysis." (PMID 36145556, 2022). "Knockdown of NRAGE promoted PCNA K48-linked polyubiquitination, leading to proteasome-dependent degradation of PCNA and cancer proliferation inhibition, and USP10 is a key regulator in this process." (PMID 36248971, 2022). "We find EGFR mutations regulate PCNA expression in NSCLC; however, there is very little evidence of how PCNA is involved in TKI failure in EGFR-mutated cancers." (PMID 36430528, 2022). "Since PCNA is overexpressed in rapidly dividing cancer cells, it acts as a potential therapeutic target against cancerous cells." (PMID 36360296, 2022). "Another protein whose expression correlates with proliferation in pancreatic and other cancers is PCNA." (PMID 36077614, 2022). "In the literature, it was shown that peptides targeting nuclear PCNA involved in DNA repair can sensitize cancer cells to existing anti-cancer therapeutics." (PMID 36430528, 2022). "Ki67 and PCNA are markers of cancer cells proliferation, high expression of them indicates the tendency to relapse and metastasis." (PMID 35291909, 2022). "PCNA is regarded as a target for inhibition and can shut down highly proliferative cells, leading to the development of cancer treatment." (PMID 35383533, 2022). "Proliferating cell nuclear antigen (PCNA) plays an important role in cancer development and progression." (PMID 36109490, 2022). "In order to interfere with this immune checkpoint and restore NK cell function against PCNA expressing cancer cell lines, we generated a monoclonal antibody that blocks NKp44-PCNA interaction, by binding membrane expressed PCNA." (PMID 35563109, 2022). "In this context, since PCNA is overexpressed in several types of cancer, but the diversity of its transcript variants in this condition is unknown, we characterized the expression, structure and implications as predictors of relapse of some novel PCNA transcript variants." (PMID 36291073, 2022). "Collectively, as proliferation is one of the hallmarks accompanying cancer development, it can therefore be assumed that increased PCNA proteins expression in OLP lesions is an ominous step that transforms a premalignant lesion to a malignant lesion." (PMID 35975803, 2022). "CCDC26 participates in cancer cell growth and apoptosis by regulating the expression of PCNA and Bcl2." (PMID 36045445, 2022). "Reduced RFC3 expression has been shown to inhibit cancer cell proliferation by forming complexes with proliferating cell nuclear antigen (PCNA)." (PMID 36686193, 2022). "PCNA has a dual function in that it is involved in DNA replication as well as DNA repair, both of which are important during cancer progression." (PMID 36686704, 2022). "PCNA and P21 were the only proteins that showed consistent evidence of clinical usefulness as cancer predictors to be considered as promising markers." (PMID 35975803, 2022).
cancer (continued). "The accumulation of PCNA in the cytoplasm of cancer cells evidenced interactions between PCNA and the proteins in the cytoplasm." (PMID 35677658, 2022). "During cell proliferation, Ki-67 and proliferating cell nuclear antigen (PCNA) are overexpressed as cell proliferation marker proteins in the cancer tissue." (PMID 33808480, 2021). "PCNA is a marker for cell proliferation and cancer virulence, and its expression is always up‐regulated in cancer cells." (PMID 34264012, 2021). "Proliferating cell nuclear antigen (PCNA) has long been thought to be a strong indicator of cancer cell proliferation." (PMID 34540679, 2021). "Proliferating cell nuclear antigen (PCNA) plays a significant role in cancer cell growth and survival by regulating DNA synthesis and repair." (PMID 33658396, 2021). "Former studies, report PCNA protein expression inhibition in mammalian cancer cells treated with different glucans including laminarin." (PMID 34940652, 2021). "The findings suggested that PCNA expression was significantly associated with poor 5-year survival, advanced stage, or higher World Health Organization grade, which indicated it might be a useful prognostic and diagnostic biomarker or an effective therapeutic target in CC or other cancers." (PMID 34721621, 2021). "As expected, the obtained UCNPs@PDL nanoprobe would carry DNA nanotrains to selectively target cancer cells and then locate in the nucleus where the anti-PCNA aptamer would specially bind with PCNA to induce the in situ release of DOX molecules." (PMID 33692990, 2021). "This is because certain cancer cells are addicted to essential pathways, where PCNA is active, and thus inhibition of PCNA can be used as a potential anticancer therapy." (PMID 33498235, 2021). "Immunohistochemistry (IHC) analysis showed that treatment with matrine resulted in a remarkably smaller proportion of proliferation marker proteins Ki-67 and PCNA positive cancer cells in tumors compared with the control group." (PMID 34642304, 2021). "Upregulation of PCNA has been reported in several types of cancer and its inhibition is gaining more interest as a novel strategy in many cancers." (PMID 34853396, 2021). "As PCNA is one of the major potential targets for cancer therapy in recent research, efforts lean towards the development of a variety of PCNA inhibiting bioactive materials, including peptides, small molecules, and aptamers." (PMID 33498235, 2021). "The overexpression also caused a decrease in expression of cancer-promoting factors EZH2, DNMT1, FOXM1, EGFR, PCNA, AURKA, YAP1, and CDH2." (PMID 34595169, 2021). "Correspondingly, both hypoxanthine and inosine restored PCNA expression in cancer cells treated with OA." (PMID 34703880, 2021). "Although baseline PCNA-Ub is significantly lower than in HCT116 cancer cells, it is detectable under unperturbed conditions." (PMID 33712616, 2021). "RFC2, CHEK1, PCNA, and POLE2 were also associated with worse overall survival in several types of cancer (Group A and D)." (PMID 34853396, 2021). "PCNA, a eukaryotic replication accessory factor, plays a critical role in cell cycle, apoptosis and proliferation in many types of human cancers." (PMID 34861846, 2021). "Consistent with the importance of the PCNA-PIP box interaction, a novel compound which specifically targets the L126 to Y133 region of the PIP-interaction loop of PCNA sensitises cancer cells to cisplatin." (PMID 35198436, 2021). "Proliferating cell nuclear antigen (PCNA) interacts with a variety of eukaryotic cell cycle-related proteins during the cell cycle process, and acts as an oncogene in a diversity of human cancers." (PMID 34180753, 2021). "Proliferating cell nuclear antigen (PCNA) facilitates and controls DNA replication and is a well‐known marker of proliferating cells in various cancers." (PMID 33314720, 2021).